RN7SKP229 (RN7SK pseudogene 229)
Gene: Miscellaneous RNA gene on chromosome 1 (181,839,473 to 181,839,774, reverse strand). Ensembl gene ENSG00000222397.
Homologues: Orthologues: chimpanzee 7SK (95% identical). Paralogues in human: RN7SKP211 (73% identical), RN7SKP217 (72% identical), 7SK (71% identical), RN7SKP133 (71% identical), RN7SKP71 (71% identical), RN7SKP9 (71% identical), RN7SKP255 (71% identical), RN7SKP79 (71% identical), RN7SKP95 (71% identical), RN7SKP130 (71% identical), RN7SKP131 (71% identical), RN7SKP203 (71% identical), and 283 more.